PACS2 (phosphofurin acidic cluster sorting protein 2)
Description:
Multifunctional sorting protein that controls the endoplasmic reticulum (ER)-mitochondria communication, including the apposition of mitochondria with the ER and ER homeostasis. In addition, in response to apoptotic inducer, translocates BIB to mitochondria, which initiates a sequence of events including the formation of mitochondrial truncated BID, the release of cytochrome c, the activation of caspase-3 thereby causing cell death. May also be involved in ion channel trafficking, directing acidic cluster-containing ion channels to distinct subcellular compartments.
Synonyms: PACS-2; KIAA0602; PACS1L; DEE66; EIEE66
Tractability: PROTAC: its protein half-life has been measured.
Gene: Protein-coding gene on chromosome 14 (105,300,563 to 105,398,147, forward strand). Ensembl gene ENSG00000179364.
Subcellular location: Endoplasmic reticulum; Mitochondrion
Subcellular location (Human Protein Atlas): Mitochondria
Gene Ontology:
Molecular function: protein binding; transmembrane transporter binding
Biological process: autophagosome assembly; endoplasmic reticulum calcium ion homeostasis; protein localization to phagophore assembly site; protein localization to plasma membrane
Cellular component: endoplasmic reticulum; mitochondrion
Genetic constraint (gnomAD): Loss-of-function variants: 27 observed, 66.38 expected, observed/expected ratio (o/e) 0.41, 90% interval 0.3 to 0.56. The upper end of that interval is the gene's LOEUF score, 0.56, which puts it in group 2 of 6, group 1 being the genes least tolerant of losing a copy. Missense variants: 797 observed, 979.31 expected, observed/expected ratio (o/e) 0.81, 90% interval 0.77 to 0.86. Synonymous variants: 477 observed, 425.65 expected, observed/expected ratio (o/e) 1.12, 90% interval 1.04 to 1.21.
Gene-disease validity (ClinGen):
ClinGen rates the evidence that PACS2 causes each of these diseases.
genetic developmental and epileptic encephalopathy (autosomal dominant): Definitive. A complex neurodevelopmental disorder characterized by a range of developmental delays and epileptic encephalopathy phenotypes.
Homologues: Orthologues: macaque PACS2 (99% identical), rat Pacs2 (95% identical), dog PACS2 (93% identical), mouse Pacs2 (93% identical), chimpanzee PACS2 (92% identical), pig PACS2 (92% identical), guinea pig PACS2 (91% identical), tropical clawed frog pacs2 (82% identical), zebrafish pacs2 (72% identical), rabbit PACS2 (52% identical), Drosophila melanogaster KrT95D (38% identical), Caenorhabditis elegans pacs-1 (26% identical). Paralogues in human: PACS1 (59% identical).
Diseases named in the same sentence as PACS2 in open-access papers:
PACS2 is named in the same sentence as 58 diseases in open-access papers, as found by Europe PMC text mining. Sharing a sentence is not in itself a finding about the gene and the disease. The quoted sentences say what the papers report.
diabetic kidney disease (9 papers, 2021 to 2026). Progressive kidney disorder caused by vascular damage to the glomerular capillaries, in patients with diabetes mellitus. "A diabetic nephropathy study reveals that phosphofurin acidic cluster sorting protein 2 (PACS2) binds to Beclin-1 and mediates the reorientation of Beclin-1 to MERCs, followed by the formation of mitophagosome." (PMID 36506093, 2022). "Targeting PACS2 is potential new strategy for the treatment of diabetic nephropathy." (PMID 35865947, 2022). "Conditional deletion of PACS2 in proximal tubules (PTs) exacerbates diabetic kidney disease (DKD) by disrupting MAM formation and mitophagy." (PMID 39668579, 2025). "In a mouse model of diabetic kidney disease (DKD), high glucose levels increased the expression of mitogen‐activated protein kinase 1, which, in turn, reduced the levels of PACS‐2." (PMID 40584408, 2025). "Here, the exact implication of phosphofurin acidic cluster sorting protein 2 (PCAS-2), an anchor protein in the MAM interface, in diabetic kidney disease was investigated." (PMID 34836936, 2021).
epilepsy (6 papers, 2023 to 2025). A brain disorder characterized by episodes of abnormally increased neuronal discharge resulting in transient episodes of sensory or motor neurological dysfunction, or psychic dysfunction. "Our results showed a heterozygous missense variant PACS2 gene leading to intellectual disability, epilepsy and cause epileptic encephalopathies (EIEE66) disorder." (PMID 38545008, 2024). "PACS2 gene mutation is associated with intellectual development disorders, autism, early onset (predominantly neonatal), epilepsy, cerebellar damage, occasional facial dysmorphisms, hematological disorders, and, in rare cases, distal limb abnormalities." (PMID 38540691, 2024). "Further, explain the possibility that PACS2 gene play important role to cause intellectual disability, epilepsy and epileptic encephalopathies in this Saudi family." (PMID 38545008, 2024). "Both PACS1 and PACS2 mutations have been reported to be associated with neurological disorders: early onset epilepsy, intellectual disability, global developmental delay, and different malformations." (PMID 38540691, 2024). "The link between epilepsy and PACS2 remains unclear, but may involve mutations affecting ion channel function, leading to seizures." (PMID 37189870, 2023). "A male patient with epilepsy, hypotonia, and ASD carried a de novo PACS2 variant, potentially contributing to the ASD phenotype and the early-onset epileptic encephalopathy through impaired ion channel regulation." (PMID 40558542, 2025). "In addition, genes related to lipid metabolism in PACS‐2 are differentially expressed in patients with epilepsy, suggesting the role of PACS‐2 in epilepsy onset and progression by regulating lipid metabolic pathways." (PMID 41456957, 2025). "PACS‐2 dysfunction may worsen epilepsy because of its significant role in lipid metabolism and neuronal activity." (PMID 41456957, 2025). "Therefore, targeting the lipid metabolism of PACS‐2 may not only improve understanding of the pathophysiological mechanisms of epilepsy but also potentially provide new strategies and directions for its treatment." (PMID 41456957, 2025).
Insulin resistance (5 papers, 2019 to 2024). Increased resistance towards insulin, that is, diminished effectiveness of insulin in reducing blood glucose levels. "Recent studies have shown that Pacs-2 is associated with insulin resistance and liver steatosis in the liver of obese mice through regulating glucose and lipid metabolism." (PMID 36138342, 2022). "Recently, literature has reported the critical role of PACS-2 in metabolic disorders such as obesity and insulin resistance." (PMID 34836936, 2021). "Phosphofurin acidic cluster sorting protein 2(PACS2) regulates cellular energy metabolism in insulin resistance, and fatty acid-CoA ligase 4(FACL4) inhibits the eNOS/NO/cGMP signaling pathway." (PMID 35865947, 2022). "Similar observations were previously noted in the liver where knockout of Pacs-2 in mice maintained on a control diet did not result in the change of whole-body adiposity, hepatic steatosis and insulin resistance." (PMID 36138342, 2022).
Epileptic encephalopathy (4 papers, 2021 to 2025). A condition in which epileptiform abnormalities are believed to contribute to the progressive disturbance in cerebral function. "Gene PACS2 (associated with AD developmental and epileptic encephalopathy 66, OMIM 618,067) was most frequently altered (seven individuals harboring rare highly deleterious heterozygous SNV)." (PMID 38539105, 2024).
Intellectual disability (4 papers, 2024 to 2025). "The key features associated with Pacs2 mutations are intellectual disability, cerebellar dysgenesis and other CNS malformations." (PMID 40533307, 2025). "PACS1, PACS2, and WDR37 variants are associated with multisystemic syndromes and neurodevelopmental disorders characterized by intellectual disability, seizures, developmental delays, craniofacial abnormalities, and autism spectrum disorder." (PMID 39031646, 2024).
atherosclerosis (3 papers, 2021 to 2022). A disease characterized by the build-up of fatty material and calcium deposition in the arterial wall resulting in partial or complete occlusion of the arterial lumen. "The results demonstrated that circ_0002194 facilitated endothelial cell dysfunction in atherosclerosis partly through upregulating PACS2 by targeting miR-637." (PMID 35951762, 2022). "As a platform to modify the phenotypic transformation of VSMCs and ECs, p66Shc and PACS-2 located on ERMCs participates in the pathological process of atherosclerosis by modifying the mitochondrial Ca2+ overload and apoptosis, which contributes to the survival of VSMCs and ECs." (PMID 34858991, 2021). "PACS2 plays an important role in ox-LDL-induced EC apoptosis by regulating the formation of MAM and the increase of mitochondrial Ca2+, suggesting that PACS2 may be a promising target for atherosclerosis." (PMID 34336087, 2021).
colon cancer (3 papers, 2013 to 2018). "Although the sample size was too small to determine the relative importance, it has been reported that the human PACS2 locus is susceptible to loss of heterozygosity in colon cancer patients." (PMID 29312533, 2017). "For example, PACS-2 is a key effector in TRAIL-mediated apoptosis, and loss of PACS-2 was shown to desensitize human colon cancer cells to TRAIL-induced apoptosis." (PMID 29312533, 2017). "Specifically, we analyzed the role of Pacs2-deficiency in a DSS-induced colitis model as well as in the genetic ApcMin colon cancer model." (PMID 29312533, 2017). "PACS-2 is an essential TRAIL effector, required for killing colon cancer cells in vitro and virally infected hepatocytes in vivo." (PMID 23658834, 2013). "PACS-2-deficient mice do not develop spontaneous neoplastic lesions in the intestine, and we recently reported that inactivation of one allele of the APC gene (ApcMin) – a commonly used model of human colon cancer – in PACS-2-deficient mice had no apparent consequence for adenoma development." (PMID 29936496, 2018).
developmental and epileptic encephalopathy (3 papers, 2021 to 2025). An epilepsy associated with developmental impairment that may be due to either the underlying etiology or the superimposed epileptic activity, or both. "Heterozygous mutations involving the PACS2 gene located on chr14:105,300,717-105,398,146 (OMIM #618067) cause developmental and epileptic encephalopathy-66 with facial dysmorphism and cerebellar dysgenesis, characterized by the onset of various types of seizures in the first days or weeks of life." (PMID 34573370, 2021).
diabetes (3 papers, 2021 to 2022). "Furthermore, PACS-2 deficiency accelerated the progression of diabetic kidney function and disruption of MAM interfaces, whereas adenoviral PACS-2 overexpression alleviated diabetes- and HG- associated ER stress, mitochondrial dysfunction, and renal tubular apoptosis and fibrosis." (PMID 34836936, 2021). "Diabetes was induced by a high-fat diet combined with intraperitoneal injections of streptozotocin (HFD/STZ) in proximal tubule-specific knockout of Pacs-2 mice (PT-Pacs-2−/− mice) and the control mice (Pacs-2fl/fl mice)." (PMID 36138342, 2022). "Besides, a recent study showed that the expression of PACS-2 decreased in the kidneys of type 1 and type 2 diabetes mice and Pacs-2 knockout mice with diabetes displayed deterioration of kidney function." (PMID 36138342, 2022). "Furthermore, PACS-2 knockout mice with diabetes displayed accelerated development of proteinuria, deterioration of kidney function, and aggravated disruption of MAM area, ER stress, mitochondrial dysfunction, renal apoptosis, and fibrosis." (PMID 34836936, 2021).
Seizure (3 papers, 2023 to 2024). A seizure is an intermittent abnormality of nervous system physiology characterized by a transient occurrence of signs and/or symptoms due to abnormal excessive or synchronous neuronal activity in the brain. "Individuals with the PACS2 c.625G>A missense mutation present with epileptic seizures early after birth and associated craniofacial and CNS malformations." (PMID 38540691, 2024).
adenoma (2 papers, 2017 to 2018). A neoplasm arising from the epithelium. "We found a similar distribution of tumors in ApcMin/+Pacs2-/-versus control mice, based on evaluation of the average number of adenomas in the proximal, middle and distal segments of the small intestine and entire colon." (PMID 29312533, 2017). "H&E staining of histological sections of adenomas in the distal small intestine revealed no obvious morphological changes between control and ApcMin/+Pacs2-/- mice." (PMID 29312533, 2017).
autism (2 papers, 2021 to 2023). Persistent deficits in social interaction and communication and interaction as well as a markedly restricted repertoire of activity and interest as well as repetitive patterns of behavior. "Interestingly, for each of the genes CIB2, FBRSL1, PACS2, KDM4B, and MYT1L, we found 2 individuals with autism with de novo variants in DAEs interacting with these genes." (PMID 34663447, 2021).
colorectal cancer (2 papers, 2017 to 2018). A primary or metastatic malignant neoplasm that affects the colon or rectum. "Accordingly, we investigated the effects of PACS-2 loss in the ApcMin mouse model of colorectal cancer." (PMID 29312533, 2017). "We therefore evaluated the effects of Pacs2-deficiency in the ApcMin mouse model of colorectal cancer." (PMID 29312533, 2017). "We observed no apparent effects of Pacs2-deficiency in the ApcMin model of colorectal cancer when assessing tumor number, size or histology." (PMID 29312533, 2017). "Here, although we observed a slight effect of Pacs2-deficiency in the context of intestinal inflammatory damage, loss of the ADAM17 fine-tuning function of PACS-2 was not sufficient to influence tumor formation driven by excessive Wnt signaling in the ApcMin model of colorectal cancer." (PMID 29312533, 2017).
developmental and epileptic encephalopathy, 66 (2 papers, 2023 to 2025). "We further reveal that mutations of PACS2 (E209K and E211K) associated with developmental and epileptic encephalopathy-66 (DEE66) impair MAM integrity through the disturbance of PACS2 phosphorylation at Ser207/208/213." (PMID 37523531, 2023). "Curiously, developmental and epileptic encephalopathy-66 (DEE66; OMIM #618067), caused by alterations in PACS2 gene, was suggested in 33 of the 38 patients analyzed." (PMID 40869285, 2025).
intestinal tumor (2 papers, 2017 to 2018). "While EGFR signaling is strongly implicated in the development of intestinal tumors, it appears that loss of the fine-tuning effects of PACS-2 is also not sufficient to impede tumor development or progression." (PMID 29312533, 2017). "The explanation why PACS-2 loss has no apparent effect on intestinal tumor formation may lie in the complex roles of PACS-2 as a phosphorylation-state dependent molecular switch that mediates either anti-apoptotic or pro-apoptotic signaling." (PMID 29936496, 2018).
liver cancer (2 papers, 2014 to 2023). An epithelial or non-epithelial malignant neoplasm that arises from the liver. "Previous studies reported that PACS2 is closely associated with the onset and progression of tumors, such as colorectal and liver cancer." (PMID 36968068, 2023). "The results of this study identify a novel mechanism by which cIAPs mediate resistance to TRAIL-induced apoptosis in liver cancer cells, namely, by regulating the formation of the PACS-2, Bim, Bax-containing signaling complex PIXosome on the lysosomes." (PMID 24633224, 2014). "Our previous studies pointed to a prominent role for cIAP-1 in TRAIL-resistance in liver cancer cells; therefore, we anticipated that cIAP-1 would be mainly responsible for PACS-2 ubiquitination." (PMID 24633224, 2014). "Together, these data suggest cIAPs constitutively downregulate PACS-2 by polyubiquitination and proteasomal degradation, thereby restraining TRAIL-induced killing of liver cancer cells." (PMID 24633224, 2014). "We have reported that PACS-2 is required for TRAIL-induced apoptosis and that inhibition of IAPs, in particular cIAP-1, sensitizes liver cancer cells to TRAIL-induced apoptosis." (PMID 24633224, 2014).
lung fibrosis (2 papers, 2022 to 2023). "Paradoxically, TRPV1 activation restores the ER–mitochondrial tethering by increasing the expression of a MAM protein named phosphofurin acidic cluster sorting protein-2 (PACS2) in pulmonary fibrosis or else favors MAM formation through the AMPK-MFN2 pathway in response to myocardial hypertrophy." (PMID 37759544, 2023). "However, TRPV1 modulation in experimental lung fibrosis had not been studied before, but our results indicate a beneficial role of CPS via modulation of TRPV1 and restoration of PACS2 protein levels and ER–mito tethering." (PMID 35212819, 2022).
type 2 diabetes (2 papers, 2021 to 2022). "In the kidneys of type 1 and type 2 diabetes mice and HG-induced HK-2 cells, a notable disruption of ER-mitochondria interactions, accompanied by a decreased PACS-2 expression in all subcellular fractions." (PMID 34836936, 2021). "We found an insufficient PACS-2 expression in all subcellular fractions in the kidney of type 1 and type 2 diabetes mice and HG-stimulated HK-2 cells, which is similar to a recent report that PACS-2 expression is decreased in different stages of DKD patients." (PMID 34836936, 2021).
channelopathies (1 paper, 2022). "On the other hand, both wild-type and mutant PACS2 (pGlu209Lys) interact with TRPV1 at different levels, implicating the importance of PACS2 in channelopathies." (PMID 35212819, 2022).
colitis (1 paper, 2017). Inflammation of the colon. "Also, while loss of ADAM17 has been shown to significantly impact both inflammation and regeneration in the DSS-induced model of colitis, PACS-2-deficient animals only displayed indications of delayed regeneration in this model." (PMID 29312533, 2017). "During the course of colitis, Pacs2-/- mice tended towards poorer survival than littermate controls (35 % vs. 61 % survival at day 10, respectively); however, this difference was not statistically significant (p = 0.08)." (PMID 29312533, 2017). "In conclusion, our data show that the effect of PACS-2 on ADAM17-mediated EGFR activation has negligible impact on DSS-induced colitis and the ApcMin model of cancer." (PMID 29312533, 2017). "Histological examination revealed severe tissue damage with numerous mononuclear cells infiltrating the lamina propria of colons on day 6 of the DSS-induced colitis model in both control and Pacs2-/- mice." (PMID 29312533, 2017). "Colon shortening, a macroscopic parameter of colitis severity, was observed to a similar extend in Pacs2-/- and control mice." (PMID 29312533, 2017). "In contrast to our findings in the DSS-induced colitis model, Pacs2-deficiency did not affect the small intestinal expression of PACS-1." (PMID 29312533, 2017). "Of note, Pacs2 mRNA expression was not significantly altered during DSS-induced colitis." (PMID 29312533, 2017). "Thus, while there was a tendency toward worse disease progression in Pacs2-/- mice undergoing DSS-induced colitis, these changes were not significant." (PMID 29312533, 2017).
coloboma (1 paper, 2025). An abnormality in which a part of a structure in one or both eyes is missing. "Ocular abnormalities like corneal opacity and coloboma are more frequent in WDR37 cases but have also been reported with PACS1 and PACS2 variants." (PMID 40869285, 2025).
disc degeneration (1 paper, 2026). "Pacs‐2 gene knockout (Pacs‐2–/–) mice developed more severe disc degeneration, with the exacerbation of ER stress, mitochondrial dysfunction, and apoptosis." (PMID 41190767, 2026).